NLRP3 (NLR family pyrin domain containing 3)
Diseases named in the same sentence as NLRP3 in open-access papers (continued):
Sharing a sentence is not in itself a finding about the gene and the disease.
periodontitis (continued). "The data indicated that the proinflammatory NLRP3+ macrophages play an important role in periodontitis and the increased cell-cell communication between macrophage and T/B cells existed in the inflammatory periodontal tissues." (PMID 34566966, 2021). "There are significant increases in the salivary levels of NLRP3, apoptosis-associated speck-like protein containing a caspase recruitment domain (ASC), and IL-1β in chronic periodontitis and aggressive periodontitis." (PMID 31900383, 2020). "The mRNA expression of the NLRP3 inflammasome complex was enhanced both in gingivitis and in periodontitis." (PMID 31900383, 2020). "Our findings demonstrated that NLRP3 inflammasome and IL-1β were both highly expressed in human gingival tissues with severe chronic periodontitis." (PMID 32903638, 2020). "Recent studies have found higher expression of IL-1β as well as NLRP3 inflammasomes in gingival tissues of periodontitis compared to healthy tissues, which is consistent with our findings in gingival tissue samples." (PMID 32903638, 2020). "The polymorphisms in NLRP3, IL1B and IL2 genes influence the development of periodontitis, independently of smoking habits." (PMID 31978095, 2020). "In periodontal disease, NLRP3 salivary levels are higher in aggressive periodontitis cases compared to periodontally healthy subjects." (PMID 32230992, 2020). "The expression of NLRP3, which is involved in inflammasomes, is higher in chronic and aggressive periodontitis gingival tissues than in healthy tissues, especially at the periodontal epithelium layer." (PMID 32230992, 2020). "Human gingiva samples were immunohistochemically characterized for the expression of NLRP3, 8OHdG, cleaved-caspase-1, and IL-1β in periodontitis specimens, compared with that in normal gingival tissues." (PMID 31685946, 2020). "It is known that inflammasomes are involved in the pathogenesis of periodontitis; however, it remains necessary to determine which inflammasomes, in addition to NLRP3, actually contribute to the pathogenesis of PD induced by P. gingivalis and F. nucleatum." (PMID 31341421, 2019). "This study aimed to explore the effect of VD3 treatment on periodontitis and AhR/NF-κB/NLRP3 inflammasome pathway in the gingival epithelium of C57BL/6 wild-type mice with experimental periodontitis induced by P. gingivalis inoculation." (PMID 31691738, 2019). "Overexpression of NLRP3 inflammasome has been found in various inflammatory diseases, including delayed soft tissue wound healing and periodontitis under diabetic conditions." (PMID 31146750, 2019). "The NLRP3 inflammasome and its effector molecules (IL-1β and caspase-1) play roles in the development of periodontitis." (PMID 31341421, 2019). "In this respect, we and others previously demonstrated the role of the NLRP3 inflammasome in the development of periodontitis." (PMID 31341421, 2019). "In this study, we examined the expressions of NLRP3, cleaved-caspase-1 (active), and IL-1β expression, each of which were upregulated in human periodontitis gingival tissue, compared to health gingiva." (PMID 29184853, 2017). "In the experimental periodontitis model, NLRP3 and IL-1β were also enhanced, similar to the results of human periodontitis specimen." (PMID 29184853, 2017). "For example, much higher NLRP3 inflammasome components were detected in periodontitis tissues than from healthy gingiva." (PMID 29184853, 2017). "The expression of NLRP3 was significantly higher in patients with chronic periodontitis and generalized aggressive periodontitis, which were mainly distributed in inflammatory cells." (PMID 28959211, 2017). "Recent studies have provided evidence that the NLRP3 inflammasome is involved in the pathogenesis of both RA and chronic periodontitis." (PMID 26078980, 2015). "Moderate expression of NLRP3 was detected in sulcular epithelium (SE) and junctional epithelium (JE) of minimally inflamed gingiva (Min), and sulcular epithelium (SE) of periodontitis (Perio) samples." (PMID 25866631, 2014).
periodontitis (continued). "Growing scientific evidence confirms the critical involvement of the NLRP3 inflammasome in various oral diseases, including periodontitis, pulpitis, periapical lesions, inflammatory disorders of the oral mucosa, and even the development and progression of oral squamous cell carcinoma (OSCC)." (PMID 41596738, 2026). "A comparison of pro-inflammatory markers (NLRP3 and IL-1β in serum and saliva) with the presence and parameters of periodontitis showed significant differences in NLRP3 levels in both saliva (p = 0.038) and serum (p = 0.021), with higher levels in patients with periodontitis." (PMID 40572711, 2025). "Increasing evidence indicated that E3s, such as CUL3, Nedd4‐2, Synoviolin, FBXL19, PDLIM2, TRIMs and TRAFs, modulate inflammatory responses and bone resorption in periodontitis through multiple classical signalling pathways, including NLRP3, GSDMD, NF‐κB, Wnt/β‐catenin and Nrf2." (PMID 39626954, 2025). "Spearman's correlation analysis was conducted to examine the relationships between variables.In saliva samples, NLRP3, caspase-1, IL-1β, and IL-18 were the highest in the periodontitis group (p < 0.005), while IL-37 was highest in the healthy group (p < 0.005)." (PMID 40267956, 2025). "Furthermore, we explored a selective small‐molecule inhibitor of METTL3 and verified its inhibitory capacity on NLRP3‐mediated pyroptosis and periodontitis." (PMID 38696610, 2024). "Taken together, it is postulated that Dioscin might be utilized as an inhibitor of NLRP3 inflammasome for the management of periodontitis and provides a reference for other NLRP3 inflammasome-related diseases." (PMID 38385066, 2024). "Furthermore, the NLRP3 inflammasome is expressed at elevated levels in periodontitis, and inhibiting its activation helps slow the progression of the disease." (PMID 39742284, 2024). "The role of O-GlcNAcylation in various diseases has been highlighted, but its impact on NLRP3 in conditions beyond periodontitis and non-alcoholic fatty liver disease remains unclear." (PMID 39742284, 2024). "Here we identified METTL3 as a regulator of NLRP3 inflammasome activation in periodontitis." (PMID 38696610, 2024). "Based on these findings, it is postulated that governing NLRP3 inflammasome might be effective in the management of periodontitis." (PMID 38385066, 2024). "Besides, the activation of NLRP3 inflammasome is commonly observed in patients with chronic periodontitis." (PMID 38181706, 2024). "The NLRP3 inflammasome is essential for periodontitis pathogenesis." (PMID 38596842, 2024). "This suggests that the inhibition of NLRP3-mediated pyroptosis may be beneficial for the amelioration of periodontitis." (PMID 39742284, 2024). "In the same study, periodontitis was found significant predictor of salivary NLRP3." (PMID 38817019, 2024). "Overall, the results established that Dioscin could alleviate periodontitis by inhibiting NLRP3 inflammasome via modulation of the K+ efflux-mtROS-ox-mtDNA pathway, holding the potential to treat periodontitis and other NLRP3-driven inflammatory diseases." (PMID 38385066, 2024). "Candidalysin directly induces pro-inflammatory factors and NLRP3 inflammatory vesicles thereby promoting an inflammatory response, and inhibition of Candida albicans by antifungal agents is effective in reducing the severity of periodontitis in women." (PMID 36923589, 2023). "This study, for the first time, demonstrates that SB exhibits the anti-inflammatory and antioxidative properties against periodontitis by downregulating the expression of NF-κB and NLRP3 and upregulating Nrf2 expression, suggesting a promising potential clinical application of SB in periodontitis." (PMID 36846719, 2023). "Furthermore, obese mice with periodontitis showed a weakened macrophage inflammatory response with a reduced expression of the NLRP3 signal pathway." (PMID 38138192, 2023). "Both NF‐κB and NLRP3 inflammasome are pivotal regulators of inflammation in periodontitis." (PMID 36446468, 2023).
periodontitis (continued). "Patients with periodontitis had considerably higher levels of NLRP3 in both their blood and saliva." (PMID 36769328, 2023). "Interestingly, the effect of NLRP3 SNPs on periodontitis distribution was assessed by counting OR and it was found 2.852, 1.500, 1.033, and 1.122 for rs10925024, rs4612666, rs34777555, and rs10754557, respectively." (PMID 36812929, 2023). "The analytic statistic in this study found a nonsignificant association of NLRP3 SNPs with demographic and clinical parameters in both periodontitis and control groups at ap-value ≥ 0.05." (PMID 36812929, 2023). "Previous studies have shown that expression levels of NF-κB and NLRP3 are significantly elevated in the periodontitis animal models, while chemical inhibitors of NF-κB and NLRP3 or their downregulation can significantly reduce the periodontitis-induced alveolar bone loss." (PMID 36846719, 2023). "Additionally, using a periodontitis mouse model, higher amounts of NLRP3 and IL-1β were visible in the inflamed gingiva." (PMID 35563469, 2022). "Periodontitis activates the NLRP3 inflammasome in serum and saliva." (PMID 35994451, 2022). "Recent studies have reported that TXNIP could induce the formation and aggregation of the NLRP3 inflammatory body, leading to dysfunction and injury of periodontal membrane fibroblasts, resulting in periodontitis." (PMID 35083332, 2022). "The NLRP3 inflammasome is overexpressed in gingiva of periodontitis patients but its role remains unclear." (PMID 35281020, 2022). "MARK4 may become a therapeutic target during the progress of periodontitis by regulating microtubule dynamics and NLRP3 inflammasome activation." (PMID 34992737, 2022). "NLRP3, as the most studied inflammasome, is activated by the infected pathogens and releasing of endogenous danger signals and then drives pathological inflammation in periodontitis 38-40." (PMID 36185327, 2022). "More recently, RIPK1, RIPK3, and MLKL have been identified to be involved in the mediation of the activation of NLRP3/caspase 1, which might contribute to the activation of pyroptosis during periodontitis." (PMID 36093182, 2022). "NLRP3 inflammasomes play a critical role in periodontitis pathogenesis." (PMID 36185327, 2022). "MARK4 inhibition might be a potential target in regulating the NLRP3 inflammasome during periodontitis progress." (PMID 34992737, 2022). "Finally, we also discuss the recently identified NLRP3 inflammasome inhibitors to provide insights into therapeutic strategies for treating periodontitis mediated by NLRP3 inflammasome." (PMID 36185327, 2022). "In what follows, we focus on the activation of NLRP3 inflammasome, the role of NLRP3 inflammasome in periodontitis pathogenesis and the therapeutic potential of NLRP3 inflammasome inhibitors in treating periodontitis." (PMID 36185327, 2022). "With the goal to provide information for future study and clinical practice, we focus on the molecular mechanisms that activate and regulate excessive NLRP3 inflammasome, then we explore NLRP3 inflammasome activation and its physiopathological consequences in periodontitis." (PMID 36185327, 2022). "Overexpression of NLRP3 in connective tissue of WT mice increased the local production of mature IL−1β, together with a dramatic mobilization of neutrophils, bipartitely distributed between the site of periodontitis induction and the alveolar bone crest." (PMID 35281020, 2022). "NLRP3 inhibitors could significantly reverse this signaling pathway’s activation and improve the symptoms of periodontitis in rats." (PMID 36710972, 2022). "This study aimed to explore whether microtubule affinity regulating kinase 4 (MARK4) can be a therapeutic target of periodontitis by affecting microtubule dynamics and NLRP3 inflammasome-mediated pyroptosis in macrophages." (PMID 34992737, 2022).
periodontitis (continued). "It is possible to conclude that NLRP3 inflammasome activation lowers osteoblast activity by lowering its bone forming ability, differentiation, and proliferation, as well as triggering pyroptosis in osteoblasts and promoting bone resorption in periodontitis." (PMID 36185327, 2022). "Aged Nlrp3−/− mice developed less alveolar bone loss compared to wild-type mice and continuous administration of MCC950 attenuated the severity of the bone loss, suggesting that NLRP3 inflammasome contributes to periodontitis progression with aging [91•]." (PMID 35567665, 2022). "However, certain studies reported that NLRP3 expression is more elevated in periodontitis patients than in healthy controls, both in specific cells, and within saliva." (PMID 34840527, 2021). "We also revealed the involvement of the proinflammatory NLRP3+ macrophages in periodontitis." (PMID 34566966, 2021). "In addition, according to a recent study, it was found that the expression of IL-1β and NLRP3 inflammasome was higher in gingival tissue of periodontitis than in normal tissue." (PMID 34356813, 2021). "It is suggested that MCC950 could inhibit the activation of NLRP3 inflammasomes in ligature‐induced periodontitis." (PMID 33382502, 2021). "Among these inflammasomes, NLRP3 has been widely studied in periodontitis." (PMID 34177950, 2021). "Within the limitations of this study, we could conclude that chronic hepatitis C and periodontitis might have a joined effect on the upregulation of the NLRP3 inflammasome and its components in the GCF." (PMID 34840527, 2021). "While studies have been performed to identify these polymorphisms individually in each disease, none of the studies have been completed so far that have quantified and correlated NLRP3 and IL-1β SNPs in subjects with chronic periodontitis and coronary artery disease." (PMID 34501201, 2021). "The activation of NLRP3/ASC/caspase 1 multiprotein complex, also known as the NLRP3 inflammasome, has recently been shown to be one of the components of innate immune responses that may impact the activity of chronic periodontitis." (PMID 34199122, 2021). "Together, we identify that the periodontitis-related bacteria could promote tumor growth and proliferation, initiate the overexpressed NLRP3, and activate upstream signal molecules of ATR-CHK1." (PMID 34660289, 2021). "Oxidative stress induces pyroptosis of osteoblast-like MG63 cells by activating the NLRP3 inflammasome, thereby attenuating bone formation and promoting periodontitis; in contrast, an NLRP3 inhibitor reverses the reduction in osteoblast migration and COL1, RUNX2, and ALP levels." (PMID 34177950, 2021). "Additional animal studies need to be conducted to decode the exact mechanism of NLRP3 inflammasome signaling in periodontitis and also the salutary action of metformin in repressing NLRP3 inflammasome activation in vivo before conducting more experiments in human subjects." (PMID 34443594, 2021). "We hypothesize that periodontitis may exhibit the expression of NLRP3 and CARD8 polymorphisms in subjects with chronic periodontitis having coronary heart disease." (PMID 34199122, 2021). "Moreover, the salivary concentration of NLRP3 is higher in patients with aggressive periodontitis than in those with chronic periodontitis." (PMID 34177950, 2021). "Polymorphisms in various inflammasome components, including NLRP3, AIM2, and IFI16, may be associated with susceptibility to periodontitis." (PMID 34177950, 2021). "In addition, the expressions of NLRP3, IL-1β, and IL-18 in gingival tissues of patients with gingivitis, invasive periodontitis, and chronic periodontitis were significantly increased." (PMID 34660289, 2021). "Pathogens of periapical periodontitis and periodontitis can activate NLRP3 in vitro." (PMID 34869060, 2021). "Salivary concentrations of ASC and NLRP3 may act as indicators of periodontal damage in periodontitis." (PMID 34177950, 2021).
periodontitis (continued). "Thus, our results suggest that NLRP3 regulates bone resorption in periodontitis by mediating osteoclast differentiation." (PMID 33382502, 2021). "The authors also found that Nlrp3 knockout could significantly decrease RANKL levels and increase OPG levels, indicating the importance of NLRP3 inflammasomes in promoting osteoclastogenesis in periodontitis." (PMID 34177950, 2021). "Xue further found that increased NLRP3 protein expression in gingival tissues with periodontitis." (PMID 32903638, 2020). "Moreover, NLRP12 was mostly distributed in the epithelium, while cells stained for NLRP3 were observed throughout the epithelium and lamina propria in periodontitis tissues." (PMID 32903638, 2020). "In addition, the polymorphisms in NLRP3, IL1R, TNF, IL6, IL2, IL4 and IL4RA genes were associated with periodontitis in the males." (PMID 31978095, 2020). "However, NLRP3, NLRP6, NLRP12, and AIM2 were expressed much higher in gingival tissues with periodontitis than in healthy group, especially for NLRP3 and NLRP12." (PMID 32903638, 2020). "The protective VD3 effect on periodontitis may correlate with the regulation of AhR/NF-κB/NLRP3 inflammasome pathway." (PMID 31691738, 2019). "As previously reported, ROS induced the activation of NLRP3 by causing thioredoxin (TRX)-interacting protein (TXNIP) to dissociate from thioredoxin, which may be associated with periodontitis." (PMID 28690552, 2017). "However, hypoxia appeared in periodontitis, in which NLRP3, cleaved-caspase-1, interleukin 1 beta (IL-1β) and caspase-1-induced cell death was enhanced in periodontitis specimens." (PMID 29184853, 2017). "Our study verified that NLRP3, cleaved-caspase-1 and IL-1β were enhanced in periodontitis tissues." (PMID 29184853, 2017). "The role of the NLRP3 inflammasome in periodontitis has recently been investigated." (PMID 27632566, 2016). "In addition, there was a positive correlation between NLRP3 and IL-1β expression levels in these tissues, confirming the involvement of NLRP3 inflammasome in the pathogenesis of periodontitis." (PMID 27632566, 2016). "Similarly, the study demonstrated a clear and distinct correlation between rs35829419 C>A in NLRP3 and rs17699678 C>T in NLRP2 polymorphism and periodontitis in the form of an increased CAL index." (PMID 26253076, 2015). "As subjects with mild chronic periodontitis have increased titres of serum antibodies auto-reactive with CD24 compared with those of subjects with severe periodontitis, a molecular mechanism for regulated expression of the NLRP3 inflammasome mediated by c-Src kinase activity, is proposed." (PMID 25866631, 2014). "Therefore, T2DM may increase NLRP3 expression in patients with chronic periodontitis, with increased IL-1β production." (PMID 41009326, 2025). "The positive correlation between salivary NLRP3 and IL-1β suggests a mutual relationship between these two markers—possibly reflecting their increased presence in periodontal tissues due to the ongoing inflammatory process in periodontitis—and their subsequent detection in saliva." (PMID 40572711, 2025). "Therefore, measuring salivary NLRP3 and IL-1β may help identify the presence and severity of chronic or aggressive periodontitis, suggesting potential value for both prevention and treatment." (PMID 41440367, 2025). "Additionally, in inflammatory environments like periodontitis, it was shown that the expression of NLRP3 inflammasome components is enhanced in response to deficient SOD2 activity, while caspase-1-IL-1β axis is also magnified, suggesting that SOD2 plays a protective role under inflammatory stimuli." (PMID 39329909, 2024). "In turn, it has been hypothesized that periodontitis, in patients with type-II DM, may contribute, through its chronic inflammatory effects supported by an abundant oral microflora, to a further upregulation of the salivary and serum NLRP3 concentrations." (PMID 38817019, 2024).